Y_RNA (Y RNA )
Gene: Miscellaneous RNA gene on chromosome 9 (67,697,076 to 67,697,187, forward strand). Ensembl gene ENSG00000275904.
Homologues: Orthologues: chimpanzee Y_RNA (100% identical), macaque Y_RNA (91% identical). Paralogues in human: Y_RNA (100% identical), Y_RNA (99% identical), Y_RNA (98% identical), Y_RNA (97% identical), Y_RNA (95% identical), Y_RNA (88% identical), RNY1P5 (87% identical), Y_RNA (87% identical), Y_RNA (86% identical), Y_RNA (85% identical), Y_RNA (84% identical), RNY1 (83% identical), and 101 more.